TGFBR2 (transforming growth factor beta receptor 2)
Diseases named in the same sentence as TGFBR2 in open-access papers (continued):
Sharing a sentence is not in itself a finding about the gene and the disease.
breast cancer (continued). "Finally, our results also highlight a strong and significant correlation between EPHA4 and TGFBR2 mRNA expression levels (r = 0.17, P < 0.0001) in more than 5000 breast cancer patients samples obtained from Breast Cancer Gene-Expression Miner v4.0 database." (PMID 29101386, 2017). "Additionally, previous studies have showed that TGFBR2 was a prognostic marker and its down regulation exhibited poor overall survival in oral cancer and breast cancer." (PMID 27008710, 2016). "The top TGFBR2 SNPs associated with breast cancer OS are not included in the GeneVar gene expression variation database." (PMID 25849327, 2015). "For instance, mutations in type II TGF-β receptor gene, TGFBR2, are frequent in human colon cancer with microsatellite instability, and down regulation of TGF-β-SMAD signaling pathway is associated with poor prognosis in breast cancer patients." (PMID 21943203, 2011). "Experimentally, they also showed that knock-down of TGFBR2 in CAFs resulted in increased cell growth, proliferation and clonogenic survival of breast cancer cells and suggest that regulation of tumour-stromal cross-talk through fibroblastic TGF-β pathway may depend on fibroblast phenotype." (PMID 26437339, 2015). "For example, TFAP2C regulates TGFBR2 transcription and promotes lung tumorigenesis and EMT, and TFAP2C regulation of CST1 transcriptional activation promotes breast cancer progression and inhibits iron death." (PMID 40995432, 2025). "In summary, a shift in the expression pattern of BMPs in breast cancer, including increased BMP8A, BMPR1B and decreased BMP6, BMP7, ACVR1C, TGFBR2, TGFBR3 and BMPR2 presented a subtype specific role." (PMID 37333824, 2023). "BMP7, GDF15, BMP5, SMAD6 and FSTL5 were highly expressed in the ER positive breast cancer cells (MCF-7 cells), while the expressions of TGFBR2, FSTL1 and NOG were reduced in this cohort." (PMID 37333824, 2023). "In summary, our results demonstrate that ALG3 overexpression promotes glycosylation of TGFBR2 and activates TGF-β signaling, which further promotes radioresistance and CSC-like traits in breast cancer." (PMID 33931075, 2021). "Some established oncogenes are also direct targets of miR-655 in other types of cancers, such as Prrx1 in breast cancer, ZEB1 and TGFBR2 in ESCC, ADAM10 in hepatocellular carcinoma, and PAX6 in retinoblastoma." (PMID 33643926, 2021). "A similar effect was observed in breast cancer when E2F1, TGFBR2, and EGFR are simultaneously active." (PMID 28775339, 2017). "In conclusion, we found that highly expressed HOXA-AS2 down-regulates miR-520c-3p, then release its targets, TGFBR2 and RELA, and promotes proliferation, migration and invasion of breast cancer cells." (PMID 28545023, 2017). "In the present study, we also explored the mechanism of the HOXA-AS2/miR-520c-3p axis in breast cancer and detected the influences of HOXA-AS2 on the targets (TGFBR2 and RELA) of miR-520c-3p." (PMID 28545023, 2017). "We demonstrated that HOXA-AS2 controls the expression of miR-520c-3p target genes, TGFBR2 and RELA, in breast cancer cells." (PMID 28545023, 2017). "3p would include TGFBR2, CNTN4, and CHL1 (reported for colorectal cancer) and CNTN6 (for breast cancer), as well as FHIT, ROBO1-GRE1 and SETMAR-LRRN1." (PMID 26247464, 2015). "The inverse correlation of combined expression of SLURP1 and negatively weighted TGFBR2 with decreased survival was also found in other breast cancer datasets even without deconvolution or the cell identification within the TME." (PMID 40568095, 2025). "For the negatively correlated gene cluster, TGFBR2 as well as TGFB1 showed a significant correlation in the same direction in the METABRIC data set, further establishing suppression of TGFß signaling by GRHL2 in breast cancer cells." (PMID 36691073, 2023). "Importantly, both glycosylation blocker, tunicamycin, and TGFBR2 inhibitor, LY2109761, reduced cancer stemness and radioresistance in ALG3-overexpressing breast cancer cells." (PMID 33931075, 2021).
breast cancer (continued). "GSEA analysis result revealed that TGFBR2 was notably enriched in the JAK STAT signaling, suggesting that ADAMTS9-AS1/miR-301b-3p/TGFBR2 signaling axis may regulate breast cancer cells through the JAK STAT signaling pathway." (PMID 34900984, 2021). "MiR-145 could inhibit cell invasion and migration by targeting TWIST in Colorectal Cancer, TGFBR2/Smad3 axis in bladder cancer, phospholipase C epsilon 1 in esophageal squamous cell carcinoma, ADAM19 in glioblastoma, and TGF-β1 in breast cancer." (PMID 32083506, 2020). "The TGF– β family is involved in most of the considered diseases, e.g., TGFB1 in Osteoporosis, TGFB3 in Rheumatoid arthritis, Osteoarthritis and Multiple myeloma, TGFBR2 in HIV, Osteomyelitis and Measles, BMP in Breast cancer and Osteosarcoma, and BMP3 in Periodontitis." (PMID 30497370, 2018). "Besides breast cancer, a putative relationship between MET and TGFBR2 expression was observed also in cell lines from other tumor entities using the NCI‐60 as well as the 789 cell line panels of the NCI and the Sanger Institute, respectively." (PMID 30004628, 2018). "Nevertheless, the exact mechanisms of TGFβ1/TGFBR2‐driven breast cancer progression and metastasis have not been fully elucidated until now." (PMID 30004628, 2018). "We could establish a positive correlation of TGFBR2 and MET protein expression in breast cancer by analyzing 801 tumor tissues samples." (PMID 30004628, 2018). "Similarly, well characterized kinases known for their relevance in breast cancer are observed, such as ERBB2, EPHA1, MET and TGFBR2." (PMID 29643987, 2018). "We identified TGFBR2 and RELA as direct targets of miR-520c-3p in breast cancer." (PMID 28545023, 2017). "We observed that decreased TGFBR2 expression in human breast cancer patients correlated with decreased CXCL1, but not with CXCL5 in HER2+, PR + and ER + tumors." (PMID 25280532, 2014). "Therefore, the observation that SOX4 and SMARCA4 mediate PI3K activity through TGFBR2 expression identifies a novel and direct role for TGFBR2 in activating noncanonical PI3K signaling in basal-like breast cancer." (PMID 33837205, 2021). "In addition, clinical studies in ER‐negative breast tumors indicated a correlation of elevated TGFBR2 levels with shorter overall breast cancer patient survival." (PMID 30004628, 2018). "Association with TGFBR2 rs1367610 but not IL12B variants replicated using BCAC Asian samples and the independent Prospective Study of Outcomes in Sporadic versus Hereditary Breast Cancer Study and yielded a combined HR of 1.57 ((95% CI 1.28 to 1.94), P = 2.05 × 10−5) without study heterogeneity." (PMID 25849327, 2015). "Keklikoglou and colleagues show that overexpression of miR-520/373 members reveals a strong downregulation of transforming growth factor-β (TGF-β) signaling and a negative correlation between miR-520c and TGFBR2 expression was observed in estrogen receptor negative (ER(-)) breast cancer patients." (PMID 25774514, 2015). "Our analysis of stromal changes between non-metastatic and metastatic canine mammary carcinomas highlighted molecular differences in the tumour microenvironment, including changes in VIT, TGFBR2, TGFBR3, LTBP4 and SFRP1." (PMID 37391533, 2023). "In line with our findings for TGFBR2, we observed higher MET expression in nonluminal compared to luminal breast cancer cell lines as well as nonluminal‐like compared to luminal‐like breast tumors." (PMID 30004628, 2018). "Gene clusters correlating positively (including known GRHL2 targets such as ErbB3, CLDN4/7) or negatively (including TGFB1 and TGFBR2) with GRHL2 in the MCF7 knockout model, display similar correlation with GRHL2 in ER positive as well as ER negative breast cancer patients." (PMID 36691073, 2023).
colorectal cancer (59 papers, 2008 to 2026). A primary or metastatic malignant neoplasm that affects the colon or rectum. "GSDMC has been reported to be upregulated by transforming growth factor beta receptor 2 (TGFBR2) mutation in colorectal cancer (CRC), promoting tumor cell proliferation." (PMID 34298833, 2021). "Microsatellite instable colorectal cancers frequently harbor inactivating mutations of the TGF‐β receptor type 2 (TGFBR2)." (PMID 33207034, 2021). "Microsatellite unstable (MSI) colorectal cancers (CRCs) are characterized by mutational inactivation of Transforming Growth Factor Beta Receptor Type 2 (TGFBR2)." (PMID 31454892, 2019). "TGF-β receptor type 2 (TGFBR2) mutations affected by a mismatch repair deficiency causes colorectal cancers (CRCs) with microsatellite instability, which is, however, associated with relatively better survival rates." (PMID 31756952, 2019). "In sporadic colorectal cancers, the TGFBR2 and SMAD4 mutations are found in about 15% and 10% of patients, respectively." (PMID 29652830, 2018). "Inactivating mutations in TGFBR2 occur in 87% of human colorectal carcinomas with microsatellite instability." (PMID 27100181, 2016). "We conducted this study to examine the prognostic significance of mononucleotide tract mutations in the coding regions of TGFBR2 or BAX in MSI-high colorectal cancers." (PMID 21949851, 2011). "Studies on prognostic significance of TGFBR2 or BAX mononucleotide mutation in MSI-high colorectal cancer." (PMID 21949851, 2011). "We compared colorectal cancer specific and overall survival between TGFBR2-mutated MSI-high cases and TGFBR2-wildtype MSI-high cases (or between BAX-mutated MSI-high cases and BAX-wild type MSI-high cases)." (PMID 21949851, 2011). "In colorectal cancer, mutations have been found in a number of genes with key cellular roles, such as growth factor receptors (TGFBR2 and IGF2R), genes involved in apoptosis (BAX), as well as genes relevant for DNA repair (MSH3, MSH6)." (PMID 20979647, 2010). "Studies of the protein and miRNA expression profiles of EVs from TGFBR2‐deficient and microsatellite instable colorectal cancers revealed an upregulation of certain ECM and nucleosomal proteins and a downregulation of proteasomal proteins in the EVs of TGFBR2‐deficient cancers." (PMID 33207034, 2021). "MSI status and TGFBR2 or BAX mononucleotide tract mutation in colorectal cancer." (PMID 21949851, 2011). "However, a role of TGFBR2 or BAX mononucleotide mutation in colorectal cancer as a prognostic biomarker remains uncertain." (PMID 21949851, 2011). "More than 90% of MSI colorectal cancers have acquired somatic insertion/deletion mutations in the coding mononucleotide repeat (A10) in exon 3 of the Transforming growth factor beta receptor type 2 (TGFBR2) gene leading to translational frameshifts and impaired receptor signaling." (PMID 26114631, 2015). "It was reported that miR-3191 promotes migration and invasion by downregulating TGFBR2 in colorectal cancer." (PMID 39696440, 2024). "Specifically, CASP8, KMT2D, RPL22 and TGFBR2 alterations tended to co-occur with GIE in patients with colorectal cancer." (PMID 37165135, 2023). "Studies have also shown that in colorectal cancer, the inhibition of the anti-metastatic gene transforming growth factor-b receptor 2 (TGFBR2) increases cell migration and invasion via miR-106a-5p." (PMID 32571262, 2020).
colorectal cancer (continued). "Mutations in TGFBR2, a component of the transforming growth factor (TGF)-β signaling pathway, occur in high-frequency microsatellite instability (MSI-H) colorectal cancer (CRC)." (PMID 27835699, 2016). "Applying a click-it chemistry protein labeling approach combined with mass spectrometry in a MSI colorectal cancer model cell line, we identified 21 de novo synthesized proteins differentially expressed upon reconstituted TGFBR2 expression." (PMID 26114631, 2015). "Our data indicated that miR-301a correlated with the metastatic and invasive ability in human colorectal cancers and miR-301a exerted its role as oncogene by targeting TGFBR2." (PMID 25551793, 2014). "More recently, Rojas and co-workers showed that TGFBR2 expression levels can affect the ability of TGFβ1 to induce p21 and apoptosis in the V-400 colorectal cancer cell line." (PMID 23951322, 2013). "In order to investigate TGFBR2-dependent changes of protein glycosylation, we sought to generate a MSI colorectal cancer cell line model system that enables inducible reconstitution of TGFBR2 expression in an isogenic background." (PMID 23468914, 2013). "In the present study, we used the TGFBR2-reconstituted MSI colorectal cancer cell line HCT116 as a model system to analyze TGFBR2-dependent alterations in protein glycosylation." (PMID 23468914, 2013). "When we separately examined TGFBR2-mutated MSI-high cases and TGFBR2-wildtype MSI-high cases, both groups showed significantly longer colorectal cancer-specific survival compared to MSS/MSI-low cases." (PMID 21949851, 2011). "MSI status, TGFBR2 and BAX mononucleotide tract mutation and survival of colorectal cancer patients." (PMID 21949851, 2011). "TGFBR2, MSH3 and MSH6 microsatellite sequences present high mutational rates in right MSI-H colorectal cancer, demonstrating that alterations in these genes are important for the development of MSI neoplasias." (PMID 20979647, 2010). "−1 bp frameshift mutations in exon 3 of TGFBR2 and exon 10 of ACVR2 are common in MSI tumors, and are thought to help drive the pathogenesis of colorectal cancers manifesting MSI." (PMID 18941508, 2008). "Moreover, PD-1 KO together with LAG-3, TIM-3, TIGIT, and TGFbR2 KO showed improved anti-tumor activity and survival compared to PD-1 alone on a colorectal cancer model." (PMID 41354926, 2025). "MiR-3139 targets TGFBR2 expression to promote cell migration and invasion in colorectal cancer." (PMID 34900984, 2021). "Mutation of TGF-β receptor type 2 (TGFBR2) leads to the microsatellite instability causing colorectal cancer, and also the loss of function of SMAD4 in the TGF-β signaling pathway promotes the tumor progression and poor survival in colorectal cancer." (PMID 33597969, 2021). "Furthermore, TGFBR2 (transforming growth factor beta receptor 2) mutations, which happen in high-frequency microsatellite instability (MSI-H) colorectal cancer (CRC), upregulate GSDMC." (PMID 34571825, 2021). "Additionally, the mutational frequency was >10% in 8 other TSGs in colorectal cancer: FAT4 (19%), TOPORS (15%), PPP2CB (13%), RASL11A (13%), PCDH9 (12%), PRDM2 (12%), LIFR (11%) and TGFBR2 (11%)." (PMID 26590405, 2016). "miR-301a promotes migration and invasion by targeting TGFBR2 in human colorectal cancer." (PMID 27230112, 2016). "In conclusion, our large tumor database has shown that, compared to MSS/MSI-low cases, MSI-high colorectal cancer is associated with longer cancer-specific survival, regardless of TGFBR2 or BAX mononucleotide tract mutation status." (PMID 21949851, 2011).
colorectal cancer (continued). "We chose patients with microsatellite instability (MSI) negative colorectal cancer in order to exclude most patients with somatically acquired TGFBR2 mutations, a common finding in MSI-positive colorectal cancer." (PMID 20500843, 2010). "In 70–90% of colorectal cancers with MSI, TGFBR2 is frameshift mutated at both alleles." (PMID 18941508, 2008). "As TGFBR2 and ACVR2 mutations may drive the pathogenesis of colorectal cancers, our human data is consistent with the virulence of tumor formation in Lynch syndrome." (PMID 18941508, 2008). "Moreover, cell lines derived from human microsatellite unstable colorectal cancers (MSI-H CRCs) with truncating mutations in TGFBR2, were not completely refractory to TGF-β, despite the lack of functional TβRII." (PMID 33478130, 2021). "It is believed that TGFBR2 plays a role involved in the occurrence and development of tumors, including NSCLC, pancreatic cancer, colorectal cancer, and liver cancer." (PMID 39364312, 2024). "An article published recently concluded that high expression of ALG10 facilitated the glycosylation of TGFBR2, stimulated TGF-β pathway and thus promoted the stemness of colorectal cancer cells." (PMID 36879254, 2023). "In colorectal cancer cells, the high expression of GSDMC can promote cell proliferation and tumor formation by inhibiting the activity of TGFBR2." (PMID 34778452, 2021). "Suppression of TGFBR2 was evident in both human endometrial epithelial and HCT116 human colorectal carcinoma ARID1AKO cells, while TGFBR2 was upregulated in OV207 cells with induced ARID1A expression." (PMID 32483112, 2020). "TGFBR2 and SMAD4 are involved in the transforming growth factor (TGF)-β pathway and were identified as driver genes in gastric cancer and colorectal cancer." (PMID 26374103, 2015). "We conducted this study to test the hypothesis that TGFBR2 or BAX mononucleotide mutations in colorectal cancer were associated with altered tumor behavior (beyond MSI), utilizing a database of 1072 stage I to IV colorectal cancers in two prospective cohort studies." (PMID 21949851, 2011). "In Affymetrix primeview human GeneChip array, we found six upregulated genes (STAT1, ATF2, TNFRSF10B, TGFBR2, BAX, and SQSTM1) and two downregulated genes (SLC4A7 and CD274) related to apoptosis and proliferation of colorectal cancer cells after hsa_circ_0064559 knockdown." (PMID 37280630, 2023). "Downregulation of TGFBR2 promotes the migration and invasion of CRC cells in colorectal cancer." (PMID 35241117, 2022). "Although the general frequencies of TGFBR2 and ACVR2 mutations are culled from general colorectal cancer cohorts, there is no experimental data on mutation rates of these targeted genes and how MMR deficiency can influence those rates." (PMID 18941508, 2008). "From the proteins annotated to the KEGG pathways colorectal cancer and PI3K-AKT signalling, one peptide of the TGF-β signalling proteins TGFB1 and TGFBR2 was detected in sEVs but not in the whole-cell lysates." (PMID 36648961, 2023).